SPATA46 (spermatogenesis associated 46)
Description:
Plays a role in spermiogenesis and fertilization.
Synonyms: C1orf111; HSD20; TEKT2BP2
Tractability: No criterion of Open Targets' tractability assessment is met for any kind of drug.
Gene: Protein-coding gene on chromosome 1 (162,373,203 to 162,376,874, reverse strand). Ensembl gene ENSG00000171722.
Subcellular location: Nucleus membrane
Gene Ontology:
Molecular function: protein binding
Biological process: fertilization; fusion of sperm to egg plasma membrane involved in single fertilization; spermatogenesis
Cellular component: nuclear membrane
Genetic constraint (gnomAD): Loss-of-function variants: 2 observed, 6.11 expected, observed/expected ratio (o/e) 0.33, 90% interval 0.13 to 1.03. That is too few expected variants to judge how well the gene tolerates losing a copy. Missense variants: 307 observed, 337.06 expected, observed/expected ratio (o/e) 0.91, 90% interval 0.83 to 1. Synonymous variants: 117 observed, 128.36 expected, observed/expected ratio (o/e) 0.91, 90% interval 0.78 to 1.06.
Homologues: Orthologues: chimpanzee SPATA46 (99% identical), macaque SPATA46 (96% identical), pig SPATA46 (77% identical), rabbit SPATA46 (75% identical), dog SPATA46 (65% identical), rat Spata46 (65% identical), mouse Spata46 (63% identical), guinea pig SPATA46 (59% identical).
Diseases named in the same sentence as SPATA46 in open-access papers:
SPATA46 is named in the same sentence as 2 diseases in open-access papers, as found by Europe PMC text mining. Sharing a sentence is not in itself a finding about the gene and the disease. The quoted sentences say what the papers report.
Globozoospermia (2 papers, 2019 to 2020). Any structural anomaly of the acrosome resulting in a round sperm head. "Studies of spermatogenesis have identified many acrosome-associated genes, such as Zpbp1, Spaca1, and Spata46 as causes of globozoospermia." (PMID 32301969, 2020).
teratozoospermia (1 paper, 2021). "Several studies have shown that protein 4.1, SPATA46, CRISP2, Spata6 and other genes play important roles in the process of normal spermatogenesis and have potential as molecular markers for clinical diagnosis of teratozoospermia." (PMID 33819193, 2021).